RNU7-125P (RNA, U7 small nuclear 125 pseudogene)
Synonyms: RNU7-135P
Gene: Small nuclear RNA gene on chromosome 16 (14,643,788 to 14,643,849, forward strand). Ensembl gene ENSG00000238964.
Homologues: Orthologues: chimpanzee U7 (100% identical), macaque U7 (100% identical). Paralogues in human: RNU7-14P (87% identical), RNU7-19P (85% identical), RNU7-30P (85% identical), RNU7-66P (85% identical), RNU7-20P (84% identical), RNU7-35P (84% identical), RNU7-73P (84% identical), RNU7-143P (82% identical), RNU7-7P (82% identical), RNU7-23P (81% identical), RNU7-37P (81% identical), RNU7-48P (81% identical), and 141 more.